MRPS26 (mitochondrial ribosomal protein S26)
Synonyms: MRP-S13; MRP-S26; C20orf193; RPMS13; dJ534B8.3; mS26; GI008; MRPS13; NY-BR-87
Tractability: Small molecule: a structure with a bound ligand is known. PROTAC: ubiquitination databases record sites on it; its protein half-life has been measured.
Gene: Protein-coding gene on chromosome 20 (3,046,041 to 3,048,254, forward strand). Ensembl gene ENSG00000125901.
Subcellular location: Mitochondrion
Subcellular location (Human Protein Atlas): Mitochondria
Pathways (Reactome):
Metabolism of proteins: Mitochondrial ribosome-associated quality control; Mitochondrial translation elongation; Mitochondrial translation initiation; Mitochondrial translation termination
Gene Ontology:
Molecular function: RNA binding
Biological process: mitochondrial translation
Cellular component: mitochondrion; mitochondrial inner membrane; mitochondrial small ribosomal subunit
Genetic constraint (gnomAD): Loss-of-function variants: 26 observed, 16.6 expected, observed/expected ratio (o/e) 1.57, 90% interval 1.13 to 1.93. The upper end of that interval is the gene's LOEUF score, 1.93, which puts it in group 6 of 6, group 1 being the genes least tolerant of losing a copy. Missense variants: 291 observed, 254.81 expected, observed/expected ratio (o/e) 1.14, 90% interval 1.04 to 1.26. Synonymous variants: 120 observed, 108 expected, observed/expected ratio (o/e) 1.11, 90% interval 0.96 to 1.29.
Homologues: Orthologues: chimpanzee MRPS26 (100% identical), rabbit MRPS26 (77% identical), dog MRPS26 (74% identical), pig MRPS26 (74% identical), guinea pig MRPS26 (73% identical), macaque MRPS26 (68% identical), mouse Mrps26 (67% identical), rat Mrps26 (67% identical), zebrafish mrps26 (44% identical), tropical clawed frog mrps26 (36% identical), Caenorhabditis elegans mrps-26 (25% identical), Drosophila melanogaster mRpS26 (23% identical).
Diseases named in the same sentence as MRPS26 in open-access papers:
MRPS26 is named in the same sentence as 3 diseases in open-access papers, as found by Europe PMC text mining. Sharing a sentence is not in itself a finding about the gene and the disease. The quoted sentences say what the papers report.
asthma (1 paper, 2024). "In addition, the expression of the MTIF3 and MRPS26 genes negatively affects the immune system’s response to asthma, impacting mitochondrial-related functions." (PMID 38783263, 2024).
tumor (2 papers, 2022 to 2024). "Mammalian mitochondrial ribosomal protein MRPS26 expression levels are correlated with tumor purity in non-small cell lung cancer (NSCLC)." (PMID 38783263, 2024).
cancer (1 paper, 2022). A tumor composed of atypical neoplastic, often pleomorphic cells that invade other tissues. "Indeed, the involvement of MRPS26 has been observed in mitochondrial activity of muscle stem cells, hinting that its expression could be central in mitochondrial degeneration during muscle atrophy-induced cancer cachexia." (PMID 36067173, 2022).